AVP (arginine vasopressin)
Diseases named in the same sentence as AVP in open-access papers (continued):
Sharing a sentence is not in itself a finding about the gene and the disease.
emotional instability (1 paper, 2023). "During periods of emotional instability, hypothalamus neurons release adrenocorticotropin-releasing hormone and arginine vasopressin, which stimulate the release of various hormones from the adrenal glands, leading to changes in the human endocrine system." (PMID 37786864, 2023).
endometritis (1 paper, 2023). An acute or chronic, usually bacterial infectious process affecting the endometrium. "OXT and AVP are important to smooth muscle contraction during parturition and lactation and are associated with endometritis, as summarized in GeneCards." (PMID 36980860, 2023).
extraventricular neurocytoma (1 paper, 2024). "In the context of SIAD and extraventricular neurocytoma, a secreting arginine vasopressin tumor must be considered." (PMID 39156001, 2024).
Glucose intolerance (1 paper, 2025). Glucose intolerance (GI) can be defined as dysglycemia that comprises both prediabetes and diabetes. "Based on findings from AVP-deficient Brattleboro rats, AVP deficiency would most likely be associated with a lower prevalence of glucose intolerance or T2D." (PMID 40428796, 2025).
Headache (1 paper, 2021). Cephalgia, or pain sensed in various parts of the head, not confined to the area of distribution of any nerve. "One of the mechanisms that can effectively improve menstrual headaches is the regulation of abnormal levels of prostaglandin F2α and plasma arginine vasopressin." (PMID 34565433, 2021).
Hyperbilirubinemia (1 paper, 2021). An increased amount of bilirubin in the blood. "Therefore, we speculate that the hyperbilirubinemia in the NIL group may be due to the low AVP circulating levels, which were not enough to activate the AVP receptor signaling mechanisms that mediate the hepatocyte bilirubin excretion." (PMID 34926704, 2021).
Hyperhidrosis (1 paper, 2010). Abnormal excessive perspiration (sweating) despite the lack of appropriate stimuli like hot and humid weather. "The findings of neurogenic deficiency of arginine-vasopressin (AVP), autonomic hyperactivity, loss of the circadian rhythm, behavioral inappropriateness, and hyperhidrosis support the involvement of the hypothalamus." (PMID 20716355, 2010).
Hypoxemia (1 paper, 2008). An abnormally low level of blood oxygen. "Hypoxemia is also reported as being a potent stimulus of fetal AVP secretion." (PMID 18828925, 2008).
Idiopathic intracranial hypertension (1 paper, 2010). "Idiopathic intracranial hypertension is possibly related to an increase in the levels of arginine vasopressin peptide in serum and cerebrospinal fluid secondary to a glucocorticoid deficient state." (PMID 20170523, 2010).
IgA nephropathy (1 paper, 2017). "To study urine concentrating capacity and AVP response in ADPKD, we performed water deprivation tests in ADPKD patients with impaired kidney function and in a control group of patients with IgA nephropathy (IgAN), matched for age, sex and eGFR." (PMID 28081165, 2017).
itch (1 paper, 2019). "Interestingly, our studies found that AVP also enhanced CQ-induced itch and V1AR antagonist significantly alleviated the OT-mediated response." (PMID 31824317, 2019).
knee osteoarthritis (1 paper, 2022). "We have previously reported increased endogenous AVP expression in formalin-induced inflammation, adjuvant-induced arthritis (AA), acute monoarthritis, and knee osteoarthritis (OA) in AVP-enhanced green fluorescent protein (eGFP) transgenic (Tg) rats." (PMID 35906406, 2022).
melancholic depression (1 paper, 2014). "In the PVN of depressed patients, the number of AVP and OXT protein expressing neurons is increased while for AVP mRNA, a 60 % increase in expression was found in the SON in melancholic but not in non-melancholic depression." (PMID 24318124, 2014).
Microprolactinoma (1 paper, 2024). A pituitary prolactin cell adenoma of less than 10 mm diameter. "A partial, mild, novel AVP deficiency was the most common permanent complication (3% in the full cohort), interestingly occurring most frequently in first surgeries of microprolactinoma." (PMID 39292628, 2024).
morphine dependence (1 paper, 2013). Strong dependence, both physiological and emotional, upon morphine. "Morphine dependence and two hours’ opiate withdrawal affected AVP and POMC mRNA levels in the hypothalamus." (PMID 23805290, 2013).
Nausea (1 paper, 2022). A sensation of unease in the stomach together with an urge to vomit. "Some evidence links nausea induced by systemic AVP with changed dominant frequency of gastric electrical slow waves (assessed by electrogastrography [EGG]), either by creating tachygastria or bradygastria." (PMID 36068676, 2022). "The effects of AVP occurred at concentrations measured in human blood plasma during nausea." (PMID 36068676, 2022).
Neurocytomas (1 paper, 2024). "Neurocytomas are neuronal tumors that can secrete arginine vasopressin and lead to SIAD." (PMID 39156001, 2024).
neuroendocrine tumors (1 paper, 2017). "It is well known that small cell lung cancer (SCLC), one of the most aggressive forms of cancer, is sometimes complicated with refractory hyponatremia because SCLC is one of neuroendocrine tumors with capability of producing AVP." (PMID 28503166, 2017). "Phenytoin might have a direct action on ectopic AVP-producing tumors, suggesting the importance of NaV channels in AVP-producing neuroendocrine tumors." (PMID 28503166, 2017). "So far, it is uncertain whether phenytoin has a direct action on ectopic AVP-producing neuroendocrine tumors." (PMID 28503166, 2017). "Conversely, ectopic AVP biosynthesis in AVP-producing neuroendocrine tumors appeared autonomous." (PMID 28503166, 2017). "It was previously uncertain whether phenytoin has a direct action on ectopic AVP-producing neuroendocrine tumors." (PMID 28503166, 2017). "Additionally, the mutational analysis and RNA interference study of NaV channels could confirm the direct involvement of NaV channels in controlling ectopic AVP expression in neuroendocrine tumors." (PMID 28503166, 2017).
neuropathic pain (1 paper, 2022). Chronic pain caused by damage to nerve fibers. "The expression kinetics of AVP and its potential involvement in the descending pain modulation system (DPMS) in neuropathic pain (NP) remains unclear." (PMID 35906406, 2022).
obstetric disorder (1 paper, 2023). Disorder associated with pregnancy, childbirth, and puerperium. "Moreover, we think that it would be really interesting to include the analysis of copeptin, another marker directly associated with AVP secretion whose role has been defined in a broad spectrum of complications, including psychiatric and obstetric disorders." (PMID 37373400, 2023).
opioid (1 paper, 2022). "The results obtained in this study showed that 12 weeks of aerobic combined with resistance exercise increased plasma OT levels, decreased plasma AVP and cortisol levels, reduced subjectively perceived stress and craving levels, and improved sleep quality in male opioid addicts." (PMID 36569629, 2022).
orthostatic intolerance (1 paper, 2018). "Unsurprisingly, AVP plays a key role in the development of orthostatic intolerance: Levels of plasma AVP increase several fold when the endpoint of cardiovascular stability (presyncope) is reached." (PMID 30774604, 2018).
postpartum depression (1 paper, 2012). A type of clinical depression that occurs after childbirth. "While it is unclear if increased maternal aggression would be a negative effect of central AVP antagonism, decreases in maternal care would be detrimental, especially in situations where care is already impaired (i.e. postpartum depression)." (PMID 24349762, 2012).
prostate tumor (1 paper, 2017). "In this work, we examined the impact of selective stimulation of V2r on key cellular events related to tumor progression through the use of the two analogs V2r agonists, dDAVP and [V4Q5]dDAVP, of the neuropeptide AVP, on lung and prostate tumor lines with NE phenotypes." (PMID 28194370, 2017).
psoriasis (1 paper, 2022). An autoimmune condition characterized by red, well-delineated plaques with silvery scales that are usually on the extensor surfaces and scalp. "The co-expression of AVP genes and IL36G was associated with psoriasis severity and therapeutic efficacy." (PMID 36172384, 2022).
pulmonary emphysema (1 paper, 2017). A subcategory of chronic obstructive pulmonary disease (COPD). "In this report, we present the hemodynamic responses to bolus administrations of AVP and noradrenaline in a patient with PH secondary to pulmonary emphysema." (PMID 29492440, 2017). "In this report, we present the hemodynamic responses to bolus administrations of AVP and noradrenaline (NAD) in a patient with PH secondary to pulmonary emphysema." (PMID 29492440, 2017).
renal cell carcinoma (1 paper, 2022). "Activation of arginine vasopressin receptor 2 (V2R) by arginine vasopressin (AVP) stimulates the cell proliferation of renal cell carcinoma (RCC)." (PMID 35011543, 2022).
Sciatica (1 paper, 2021). Pain in the lower back and hip radiating in the distribution of the sciatic nerve. "In patients with sciatica, pain reduction following EA is correlated with increased arginine vasopressin levels (AVP) as AVP triggers descending pain inhibition following increased NA levels in the hypothalamus." (PMID 34069357, 2021).
spindle cell sarcoma (1 paper, 2025). A malignant mesenchymal neoplasm composed of spindle-shaped cells. "This is a case of partial arginine vasopressin resistance following the sixth cycle of doxorubicin-ifosfamide-mesna therapy for recurrent spindle cell sarcoma of the thigh." (PMID 40497202, 2025).
squamous cell carcinoma (1 paper, 2016). A carcinoma arising from squamous epithelial cells. "In 2004, Lee proposed that neuropeptide Y is increased in squamous cell carcinoma patients which in turn increases endogenous AVP production leading to SIADH." (PMID 27635269, 2016).
sudden cardiac arrest (1 paper, 2025). Unexpected rapid natural death due to cardiovascular collapse within one hour of initial symptoms. "There are reports suggesting that ischemia could also lead to cytotoxic edema due to fluctuations in the arginine vasopressin system; however, hypoxia did not contribute to these changes in our patient’s case, as there was no incident of sudden cardiac arrest (SCA)." (PMID 40843878, 2025).
Ureteral obstruction (1 paper, 2019). Obstruction of the flow of urine through the ureter. "In this study, we investigated the AVP-independent regulation of AQP2 by TAM and the therapeutic effect of TAM on the dysregulation of AQP2 and impaired urinary concentration in a unilateral ureteral obstruction (UUO) model." (PMID 31447686, 2019).
Urinary retention (1 paper, 2025). Inability to completely empty the urinary bladder during the process of urination. "Increased responsiveness of the collecting ducts to arginine vasopressin has been observed in elderly patients with urinary retention." (PMID 40485652, 2025).
Williams syndrome (1 paper, 2015). "Williams syndrome (WS) is a condition caused by a deletion of ∼26–28 genes on chromosome 7q11.23 often characterized by abnormal social behavior and disrupted oxytocin (OT) and vasopressin (AVP) functioning." (PMID 25741359, 2015).
tumor (46 papers, 1999 to 2026). "It has been demonstrated that these tumor cells have either over expressed V1a receptors or have a mutated form of V1a receptor leading to increased sensitivity to AVP causing increased secretion of corticosteroid." (PMID 25853137, 2015). "The pathophysiology of SIADH in chronic conditions such as pulmonary malignancies, especially in tumors of small cell lung cancer, is related to the tumor production of ADH, also known as arginine-vasopressin (AVP)." (PMID 39949461, 2025). "SIAD is difficult to manage in the setting of a tumor-producing arginine vasopressin and, in the setting of subtotal resection, can be treated with empagliflozin and fluid restriction." (PMID 39156001, 2024). "The vast majority of the tumor cells were positive for anti-arginine vasopressin antibody (self-made polyclonal rabbit antibody)." (PMID 39156001, 2024). "In the case of ectopic expression of AVP, AVP-producing tumor cells are generally detected in the lung, pancreas, or other tissues." (PMID 34289912, 2021). "The data summarized above suggest an important role for AVP and AVP-blocking drugs in regard to cellular proliferation, regeneration, and the growth of neoplasms." (PMID 25853137, 2015). "Staining for arginine vasopressin (ADH) in the tumor tissue can also be done to help support the diagnosis." (PMID 23259127, 2012). "SIADH could be induced by some drugs including anxiolytics and narcotic drugs or may result from ectopic production of the antidiuretic hormone, arginine vasopressin (AVP) by the tumor tissue." (PMID 32996719, 2020). "In exact, BRCA1-null tumor cells corresponded to mesenchymal, basal and AvP lineages." (PMID 32840210, 2020). "Arginine vasopressin is detected in up to two-thirds of SCLC tumours whereas normal physiological expression is essentially restricted to the hypothalamus." (PMID 10471042, 1999). "Interestingly tumors may produce and secrete AVP, in addition to expressing AVPR2, thus favoring self-maintenance and proliferation of the tumor itself." (PMID 39125971, 2024).
cancer (43 papers, 2008 to 2025). A tumor composed of atypical neoplastic, often pleomorphic cells that invade other tissues. "Our analysis revealed that, among the genes studied, CLEC11A, ICAM4, ITGA4, and AVP exhibited the highest specificity to AML when compared to other cancer types." (PMID 39484036, 2024). "In cancer patients, this syndrome is mostly secondary to ectopic secretion of arginine vasopressin by tumoral cells." (PMID 36831539, 2023). "This SIADH is driven by the release of arginine vasopressin (AVP, also known an antidiuretic hormone) by cancer or by effects of anticancer medications." (PMID 34185420, 2021). "SIADH include disorders of the central nervous system, intrathoracic disorders and drug administration, in addition to ectopic production of AVP in cancer tissues." (PMID 29088071, 2017). "Ectopic production of AVP is clear, because AVP is ectopically synthesized in several cancer tissues and directly released into the systemic circulation." (PMID 29088071, 2017). "We found that although the VASO gene of AVP (arginine vasopressin) was not significantly regulated in any of the three cancer nodules, expressions of several other genes were significantly altered (though not in the same way) in all profiled regions." (PMID 38132440, 2023). "Third, protein interaction networks of unique DEGs of the two voles relabeled that among the severe hypoxia-specific DEGs in L. mandarinus, the most prominent core genes were RLN3, AVP, CALCA, and SOX2, which regulate responses to stress, metabolism, and cancer." (PMID 32256671, 2020). "There are two sources of AVP in SIADH: ectopic production of AVP in lung, pancreatic and other cancers, and increased central secretion of AVP from the hypothalamo-neurohypophyseal system due to central nervous system disorders, intrathoracic disorders or drugs." (PMID 29088071, 2017).
infection (27 papers, 2013 to 2026). The state of being infected such as from the introduction of a foreign agent such as serum, vaccine, antigenic substance or organism. "In infections of the lower respiratory tract, endotoxins and acute-phase cytokines stimulate the secretion of AVP, along with which, copeptin is synthesized in equimolar amounts." (PMID 36004962, 2022). "We also show that castration post establishment of chronic infection precludes changes in fear and medial amygdala arginine vasopressin in the infected male rats." (PMID 32714222, 2020). "The expression of the potential AVP gene cecropin A and cecropin B also tended to be up-regulated during infection with B. mori cytoplasmic polyhedrosis virus (BmCPV), but expression levels were too low to be considered as biologically important." (PMID 32983149, 2020). "Hormones including AVP play an important role in the manner in which responses to infection are modulated." (PMID 25853137, 2015). "Important cellular responses including cell proliferation, inflammation, and control of infection and their relationship to AVP are described." (PMID 25853137, 2015). "Thus, live spores through natural infection appear to elicit an IgA biased response, in contrast to that generated through AVP protein vaccination, which exhibits IgG bias." (PMID 26322022, 2015). "The results showed that high infection rates in AVP-positive neurons (56.68%) and CRH-positive neurons (25.93%), whereas infection of OXT-positive neurons was minimal (9.09%)." (PMID 41543628, 2026). "MG, AVP, and ORT were detected in backyard flocks, and concomitant infection with IBV was found in two backyard flocks and all three submissions of commercial layer flocks." (PMID 33921858, 2021). "This infection creates AVP hypomethylation within medial amygdala while not affecting the PVN." (PMID 30863290, 2019).